SPDYE21 (speedy/RINGO cell cycle regulator family member E21)
Synonyms: SPDYE21P
Gene: Protein-coding gene on chromosome 7 (67,276,941 to 67,289,005, forward strand). Ensembl gene ENSG00000230358.
Gene Ontology:
Molecular function: protein kinase binding
Genetic constraint (gnomAD): Loss-of-function variants: 12 observed, 24.56 expected, observed/expected ratio (o/e) 0.49, 90% interval 0.31 to 0.79. The synonymous counts are far from expectation, so gnomAD's model fits this gene poorly and the ratio says little. Missense variants: 181 observed, 284.17 expected, observed/expected ratio (o/e) 0.64, 90% interval 0.56 to 0.72. Synonymous variants: 39 observed, 96.34 expected, observed/expected ratio (o/e) 0.4, 90% interval 0.31 to 0.53.
Homologues: Orthologues: mouse Spdye4a (33% identical), rat Spdye4 (33% identical), mouse Spdye4b (29% identical). Paralogues in human: SPDYE5 (95% identical), SPDYE2 (95% identical), SPDYE2B (94% identical), SPDYE6 (94% identical), SPDYE1 (88% identical), SPDYE18 (84% identical), SPDYE16 (83% identical), SPDYE3 (62% identical), SPDYE12 (54% identical), SPDYE13 (54% identical), SPDYE14 (54% identical), SPDYE15 (54% identical), and 6 more.